REG3G (regenerating family member 3 gamma)
Description:
Bactericidal C-type lectin which acts exclusively against Gram-positive bacteria and mediates bacterial killing by binding to surface-exposed carbohydrate moieties of peptidoglycan. Restricts bacterial colonization of the intestinal epithelial surface and consequently limits activation of adaptive immune responses by the microbiota. Acts as a hormone in response to different stimuli like anti-inflammatory signals, such as IL17A, or gut microbiome. Is secreted by different cell types to activate its receptor EXTL3 and induce cell specific signaling pathways. Induced by IL17A in keratinocytes, regulates keratinocyte proliferation and differentiation after skin injury. In parallel, inhibits skin inflammation through the inhibition of inflammatory cytokines such as IL6 and TNF. Induced by IL22 in lung epithelial cells, inhibits cytokine production and regulates allergic airway inflammation. Induced in small intestine by inulin-enriched diet and Lactobacillus gasseri enriched microbiome, plays a role in the improvement of gut barrier function, the regulation of energy balance and glucose levels. Modulates microbiota composition in duodenal contents. Produced by nociceptor in response to endotoxins, prevents endotoxic death by targeting kynurenine pathway in microglia. [Regenerating islet-derived protein 3-gamma 16.5 kDa form]: Has bacteriostatic activity. [Regenerating islet-derived protein 3-gamma 15 kDa form]: Has bactericidal activity against L.monocytogenes and methicillin-resistant S.aureus.
Synonyms: PAP-1B; PAP IB; REG III; PAP1B; UNQ429; LPPM429; PAPIB; REG-III
Tractability: Antibody: its Gene Ontology location is reachable by antibodies, with high confidence; UniProt places it where antibodies can reach, with medium confidence; UniProt predicts a signal peptide or a membrane-spanning region.
Gene: Protein-coding gene on chromosome 2 (79,025,686 to 79,028,505, forward strand). Ensembl gene ENSG00000143954.
Subcellular location: Secreted; Cytoplasm
Subcellular location (Human Protein Atlas): Cytosol; Predicted to be secreted
Pathways (Reactome):
Immune System: Antimicrobial peptides
Gene Ontology:
Molecular function: oligosaccharide binding; peptidoglycan binding; growth factor activity; hormone activity; carbohydrate binding
Biological process: antimicrobial humoral immune response mediated by antimicrobial peptide; defense response to Gram-positive bacterium; MyD88-dependent toll-like receptor signaling pathway; negative regulation of keratinocyte differentiation; positive regulation of cell population proliferation; positive regulation of keratinocyte proliferation; positive regulation of wound healing; response to peptide hormone
Cellular component: cytoplasm; extracellular region
Genetic constraint (gnomAD): Loss-of-function variants: 20 observed, 20.58 expected, observed/expected ratio (o/e) 0.97, 90% interval 0.68 to 1.41. The upper end of that interval is the gene's LOEUF score, 1.41, which puts it in group 5 of 6, group 1 being the genes least tolerant of losing a copy. Missense variants: 235 observed, 209.51 expected, observed/expected ratio (o/e) 1.12, 90% interval 1.01 to 1.25. Synonymous variants: 89 observed, 80.44 expected, observed/expected ratio (o/e) 1.11, 90% interval 0.93 to 1.32.
Homologues: Orthologues: chimpanzee REG3G (96% identical), macaque REG3G (91% identical), dog REG3A (77% identical), zebrafish si:dkey-241l7.4 (27% identical), zebrafish si:dkey-241l7.5 (27% identical), zebrafish zgc:172053 (27% identical), Caenorhabditis elegans clec-150 (26% identical), zebrafish si:ch211-125e6.11 (26% identical), zebrafish si:ch211-125e6.5 (26% identical), zebrafish si:dkey-241l7.2 (26% identical), zebrafish si:dkey-241l7.3 (26% identical), zebrafish si:dkey-241l7.6 (26% identical), and 10 more. Paralogues in human: REG3A (85% identical), REG1A (47% identical), REG1B (47% identical), REG4 (30% identical), CLEC19A (28% identical).
Diseases named in the same sentence as REG3G in open-access papers:
REG3G is named in the same sentence as 70 diseases in open-access papers, as found by Europe PMC text mining. Sharing a sentence is not in itself a finding about the gene and the disease. The quoted sentences say what the papers report.
colitis (26 papers, 2010 to 2024). Inflammation of the colon. "Consistent with this, reg3g complement effectively attenuated colitis severity in TAGAP-deficient mice." (PMID 36704549, 2022). "Furthermore, another member of pancreatitis-associated proteins, Reg3g, was upregulated in an experimental colitis mouse model when treated with eckol at doses of 0.5–1.0 mg/kg." (PMID 35209235, 2022). "We also showed that this sequence can be disrupted - and colitis severity greatly attenuated - either by restoring gut microbiome homeostasis (via replacement of gut reg3g), or by directly attenuating the pathogenic function of the colitogenic CD4+ T cell population (via p40 inhibition)." (PMID 36704549, 2022). "This is in agreement with studies in the Il2-/- mouse model, where increased expression levels of Reg3b and Reg3g genes might be associated with prevention of colitis triggered by colonization with commensal E. coli." (PMID 20630110, 2010). "Card9 gene directly contributes to recovery from dextran sodium sulfate (DSS)-induced colitis by inducing the colonic expression of the cytokine IL-22 and the antimicrobial peptides Reg3β and Reg3γ independently of the microbiota." (PMID 38649950, 2024). "Alistipes finegoldii mediates protection from dextran sodium sulfate (DSS)-induced colitis by restoring intestinal barrier function through the enhanced colonic expression of intestinal IL-22 and Reg3γ." (PMID 38303112, 2024). "The rectal delivery of human hREG3A (homolog to mouse Reg3γ) in mice alters the intestinal microbiota and controls colitis inflammation in mice." (PMID 38501032, 2024). "Studies in mice suggest that Reg3γ is a downstream mediator of IL-33 and has a protective role in colitis by reducing inflammation and oxidative stress." (PMID 37524871, 2023). "Both Lcn2 and Reg3g exhibited significantly increased expression in Bmal1+/+ control colon tissue following induction of DSS-colitis." (PMID 35223537, 2022). "Since Reg3g appeared to be a protection against the colon injury development, the authors suggested the possibility of using 2 as an alternative treatment of colitis." (PMID 35209235, 2022). "The expressions of Reg2, Reg3b, and Reg3g tended to be increased in the DSS-colitis mice, suggesting the existence of inter-organ communication signals between the pancreas and colon during intestinal inflammation." (PMID 33594081, 2021). "We examined this idea further by determining the expressions of genes encoding four antimicrobial proteins (regenerating islet-derived [Reg] family protein 2, Reg3α, Reg3β, and Reg3γ) in the pancreas of DSS-colitis mice." (PMID 33594081, 2021). "While these antimicrobial peptides are expressed in an Irgm1-dependent fashion during DSS colitis, surprisingly, Reg3γ and Reg3β were robustly expressed by Irgm1-/- mice in response to C. rodentium infection." (PMID 32453761, 2020). "When colitis was induced, in all groups, the clear expression pattern of Muc2, Reg3b, and Reg3g was lost, but Clec7a, Clec4n, and Il22 mRNA expression was still increased in HSD- vs. CD-fed mice." (PMID 33339337, 2020). "Thus, we hypothesis that RAI16 knockout could suppress the secretion of IL-18 and the expression of IL-22 binding protein (IL-22BP) in intestinal epithelial cells, consequently downregulate the secretion of STAT3-dependent Reg3γ and Reg3β, all together, which induces dysbiosis linked colitis." (PMID 31862898, 2019). "Regardless of the mechanisms of Reg3 gene and Ang-4 gene regulation, there seems to be an inverse correlation between Reg3β, Reg3γ, and Ang4 gene expression levels and the location of colitis in Muc2−/− mice." (PMID 22723890, 2012). "The decreased production of IL-22 in ILC3s may contribute to the observed dysregulation of Reg3b and Reg3g in Npm1+/− mice in DSS-induced colitis, and thus impaired intestinal microbiota homeostasis." (PMID 39103576, 2024).
colitis (continued). "DSS-induced colitis is aggravated in Reg3β KO mice relative to wild-type mice, suggesting that attenuation of colitis and ileitis is dependent on the function of Reg3β miRNA knockdown of Reg3β and Reg3γ promotes colitis in mice." (PMID 38501032, 2024). "During acute colitis in mice, IL-33 and Reg3γ are highly expressed in the colon." (PMID 37524871, 2023). "These recent reports imply that the protective effect of propionate on experimental colitis could be mediated through Reg3γ." (PMID 37524871, 2023). "We then tested whether the administration of recombinant reg3g protein has any therapeutic effect in the DSS-induced colitis model." (PMID 36704549, 2022). "In mice with dextran sulfate sodium (DSS)-induced colitis, Reg3γ protein expression was upregulated and the STAT3-associated cytokines (such as IL-6, IL-17, and IL-22)/Reg3γ axis played a pivotal role in the acute phase of colitis." (PMID 34811636, 2022). "Thus, the profound induction of Reg3b and Reg3g in GP130ΔSTAT/+ mice strongly implicates that IL-6ST/gp130/STAT3 signalling contributes to the regulation of host microbiome composition during colitis." (PMID 33673239, 2021). "In addition, the levels of the intestinal barrier integrity marker, the regenerating islet-derived protein 3γ (REG3γ), were also found reduced in colitis mice treated with SuperMApo." (PMID 35003066, 2021). "The inverse correlation between colitis development and Reg3β, Reg3γ, and Ang4 expression levels might point toward a role for these innate defense peptides in regulating intestinal inflammation." (PMID 22723890, 2012). "Finally, morphological signs of colitis were only observed in the distal colon of Muc2−/− mice at P28, where and when expression levels of Reg3β, Reg3γ, and Ang4 were the lowest." (PMID 22723890, 2012). "Additionally, the levels of Reg3γ were significantly reduced in IL‐22 KO memory‐effector transfer mice, suggesting that IL‐22 may drive colitis by inducing REG3γ, that may alter the microbiota composition and lead to dysbiosis." (PMID 38363052, 2024). "When Reg3 proteins and/or Ang4 indeed limit intestinal inflammation one might even speculate that the distal colon is more prone to develop colitis than the proximal colon because Reg3β, Reg3γ, and Ang4 expression levels are lower in the distal colon than in the proximal colon." (PMID 22723890, 2012). "The observed upregulation of Reg3g and Fut2 by DKT in the colonic epithelial cells prompted us to interrogate the involvement of IL-22 in DKT-mediated amelioration of colitis." (PMID 35720414, 2022). "We therefore tested the expression of AMPs in untreated mice and mice treated with DSS to induce colitis (all samples collected at ZT16, when Reg3g and Lcn2 have been shown to be higher)." (PMID 35223537, 2022). "Regenerating islet-derived protein 3 gamma and beta (REG3G and REG3B), antimicrobial C-type lectins, appear to be important in inflammatory diseases and intestinal injury as their expression is increased in IBD patients and in DSS models of murine colitis." (PMID 23894361, 2013). "Regenerating islet-derived protein 3 beta (Reg3β), Reg3γ and HIP/PAP appear to be important in inflammatory diseases and intestinal injury as their expression is increased in IBD patients and in dextran sulfate sodium models of mouse colitis." (PMID 22723890, 2012). "To evaluate the expression of antibacterial peptides in colitis, we examined the expression levels of antimicrobial peptide genes in colon tissue, finding that the MOP treatment reversed the DSS-induced decrease in mRNA expression levels of both Reg3b and Reg3g." (PMID 35911761, 2022). "Furthermore, morphological signs of colitis were observed in the distal colon of Muc2−/− mice, where expression levels of Reg3β, Reg3γ, and Ang4 mRNAs were the lowest, but not in the proximal colon where expression levels of these genes were the highest." (PMID 22723890, 2012).
colitis (continued). "Namely, morphological signs of colitis are only observed in the distal colon of Muc2−/− mice at P28, where and when the expression levels of Reg3β, Reg3γ, and Ang4 were the lowest, but not in the proximal colon, where Reg3β, Reg3γ, and Ang4 levels were the highest." (PMID 22723890, 2012).
Obesity (7 papers, 2017 to 2024). Accumulation of substantial excess body fat. "Overall, these results indicate that loss of REG3β or REG3γ is insufficient to aggravate diet-induced obesity and NAFLD." (PMID 30392013, 2019). "We also offered evidence for critical cellular links among REG3γ-associated Lactobacillus, tissue macrophages, and obesity diseases." (PMID 28928739, 2017). "Meanwhile, we also found a critical cellular link among REG3γ-associated Lactobacillus, tissue macrophages, and obesity diseases." (PMID 28928739, 2017). "Gut REG3γ-associated Lactobacillus may have capacities to impede the onset of obesity through increased gut anti-inflammatory macrophages." (PMID 28928739, 2017). "Anti-inflammatory macrophages in the lamina propria, which are induced by REG3γ-associated Lactobacillus, may migrate into adipose tissues and are involved in resistance against high-fat diet-mediated obesity." (PMID 28928739, 2017). "Similar to chronic ethanol consumption, animal models of diet-induced obesity indicate a downregulation of intestinal Reg3γ." (PMID 30392013, 2019). "Another recent study, however, showed that neither Reg3γ deficiency nor intestinal overexpression affected diet-mediated obesity and glucose dysregulation." (PMID 37524871, 2023). "Recent rodent studies from our laboratory and others reported that the expression of intestinal Reg3γ is downregulated in metabolic disorders induced by nutrition (high-fat diet, alcohol) or genetic modification (ob/ob, db/db) that result in obesity and impaired glucose regulation." (PMID 37524871, 2023). "Moreover, treatment of human keratinocytes with palmitic acid, a fatty acid mainly involved in obesity, induces the expression of Th17 cell-related cytokines with Regenerating islet-derived protein 3 gamma (Reg3γ), which results in epidermal hyperplasia, like psoriasis." (PMID 39204094, 2024). "However, Reg3γ is downregulated in metabolic disorders such as obesity and type 2 diabetes." (PMID 37524871, 2023). "In this study, berberine treatment not only reduced obesity but also considerably decreased the concentration of TNF-α, iNOS, Cox-2, and Reg3γ." (PMID 35095784, 2021).
chronic pancreatitis (5 papers, 2016 to 2024). A chronic inflammatory process causing damage and fibrosis of the pancreatic parenchyma. "In an in-vivo study, the caerulein-induced chronic pancreatitis mouse model was co-injected for 16 weeks with dimethylbenzanthracene and pReg3g, the latter of which was a lentivirus system encoding for murine Reg3g." (PMID 31921694, 2019). "In a mouse model of caerulein-induced chronic pancreatitis, Reg3γ overexpression accelerated pancreatic tumorigenesis, suggesting that Reg3γ aggravated inflammation and neoplastic progression." (PMID 39857608, 2024). "And the addition of high dose of pReg3g were reported to develop recognizable tumors in pancreas in mice with chronic pancreatitis, which indicated that Reg3g expression exacerbated pancreatic cancer in inflammation-associated cancer progression." (PMID 31921694, 2019). "We previously demonstrated that Reg3g promoted pancreatic carcinogenesis via a STAT3 signaling pathway in a murine model of chronic pancreatitis." (PMID 28880262, 2017). "Reg3g is a soluble small protein, rarely secreted in the normal pancreas, but markedly overexpressed during acute or chronic pancreatitis." (PMID 28880262, 2017). "Recently, both mouse Reg3β and Reg3g have been reported to promote the transition from chronic pancreatitis to PDAC by using a caerulein-induced pancreatitis mouse model." (PMID 27788482, 2016). "Recently, Reg3G was detected in urine obtained from experimentally induced chronic pancreatitis." (PMID 33027970, 2020).
pancreatic cancer (5 papers, 2017 to 2025). "The expression of Reg3A was significantly upregulated in pancreatic, liver, and colorectal cancer in humans, while significant upregulation of Reg3G has been specifically noted in pancreatic cancer." (PMID 33027970, 2020). "Reg3G has been reported to function as an immunosuppressive promoter by suppressing the antitumor effects of T cells in a murine model of pancreatic cancer." (PMID 33027970, 2020). "Among them, Reg3G has been reported to be related to pancreatic cancer." (PMID 33027970, 2020). "Therefore, we established orthotopic or ectopic mouse models of pancreatic cancer, and found that Reg3g overexpression promoted tumor growth by accelerating Ki67 and inhibiting the cell apoptosis-related protein caspase-3." (PMID 28880262, 2017). "However, Reg3g overexpression sped up the formation of pancreatic tumors as confirmed by histologic analysis." (PMID 28880262, 2017). "The results of this study generally support the hypothesis, revealing a novel mechanism for pancreatic tumor promotion by Reg3g." (PMID 28880262, 2017). "Flow cytometry analysis (FACS) revealed that Reg3g overexpression also decreased the population of CD3+CD8+ T cells, and augmented the frequency of Tregs in the spleen and lymph node of the orthotopic pancreatic tumor mice." (PMID 28880262, 2017). "To validate whether Reg3g, the mouse homolog of human REG3A, modulates pancreatic tumor growth via alteration of the TME composition in vivo, we established Reg3g-conditioned Panc02 cells, which exhibited upregulated Reg3g, and then implanted them into mice." (PMID 28880262, 2017).
pancreatitis (5 papers, 2006 to 2020). Inflammation of the pancreas. "Reg3G has been identified as a pancreatitis-associated protein released by the acini during acute pancreatitis and injury." (PMID 33027970, 2020). "Reg3 subfamily, including Reg3A and Reg3G, are known as pancreatitis-associated proteins due to their activation in response to inflammatory stimuli." (PMID 27788482, 2016). "Three genes, linked to pancreatitis and cancer, the regenerating islet-derived 3 alpha, beta and gamma (Reg3a, Reg3b and Reg3g), were increased by more than 100-fold by AMPH within 3 hr, but not by EIH." (PMID 23497014, 2013).
alcoholic steatohepatitis (4 papers, 2016 to 2024). "The overexpression of Reg3g in mice led to a decrease in mucosa-associated microbiota and prevented the translocation of bacteria, thus protecting the animals from developing alcoholic steatohepatitis." (PMID 38674014, 2024). "Mice deficient in the Reg3g gene developed alcoholic steatohepatitis, confirming the protective role of REG3G in ARLD." (PMID 38674014, 2024). "Studies have documented that ethanol causes a downregulation of REG3G and REG3B in the small intestine and that the liver is protected against alcoholic steatohepatitis in case of REG3G hyper-expression." (PMID 34886561, 2021). "Therefore, mice receiving bio-engineered Lactobacillus reuteri restored levels of both IL22 and Reg3g and further improved alcoholic steatohepatitis." (PMID 31540133, 2019).
inflammatory bowel disease (4 papers, 2015 to 2025). A spectrum of small and large bowel inflammatory diseases of unknown etiology. "For instance, a sequential treatment involving probiotics, a Mediterranean diet, and FMT activates the Akkermansia-mediated IL-22/REG3γ pathway, leading to substantial synergistic effects in promoting mucosal healing in models of inflammatory bowel disease." (PMID 40661744, 2025). "In inflammatory bowel disease expression of the secreted mucus protein Muc2 is downregulated while Reg3g expression is increased indicating that Reg3g expression increases when the mucus layer is disassembled." (PMID 26783537, 2016). "For Reg3g an increase in expression levels was observed in IBD (inflammatory bowel disease), a murine bacterial reconstitution model and after experimental intestinal infection with Listeria monocytogenes." (PMID 26329040, 2015).